SIRT3 (sirtuin 3)
Diseases named in the same sentence as SIRT3 in open-access papers (continued):
Sharing a sentence is not in itself a finding about the gene and the disease.
osteoporosis (continued). "Regulation of mitophagy was another mechanism for SIRT3 to reduce the senescence of BMSCs and senile osteoporosis." (PMID 35692409, 2022). "In conclusion, the results of the present work reveal that mitochondrial deacetylase Sirt3 is a major contributor of the increased bone resorption in the pathogenesis of osteoporosis." (PMID 33878033, 2021). "In summary, our study showed that melatonin ameliorates mitochondrial oxidative stress to improve bone mass around prostheses in osteoporosis via the SIRT3/SOD2 signaling pathway." (PMID 31110599, 2019). "Our study proved that melatonin ameliorates mitochondrial oxidative stress in osteoporosis, promotes osteogenesis, and increases bone mass around prostheses via the SIRT3/SOD2 signaling pathway." (PMID 31110599, 2019). "As aging is associated with reduced Sirt1 level and activity, the influence of STACs on Sirt3 needs to be investigated in vivo in animal and human disease models of aging and osteoporosis." (PMID 26226624, 2015). "In mouse models, SIRT3 overexpression alleviated age-induced senescence and promoted the osteogenic differentiation of bone marrow mesenchymal stem cells, thereby preventing osteoporosis through the activation of mitophagy." (PMID 41304967, 2025). "This complex phenomenon suggests that SIRT3 may affect the biological behaviour of senescence‐related osteoblasts through multiple pathways and play a dual role in osteoporosis, but more in‐depth studies are still required to clarify the mechanisms." (PMID 40681473, 2025). "Given the sexual dimorphic role of SIRT3 in the development of osteoporosis and other diseases, it is possible that an increase in osteoclast activity and bone loss with IR exposure might occur predominantly in females." (PMID 40584154, 2025). "Additionally, SIRT3 is crucial for osteoclast mitochondrial activity and bone resorption during the progression of osteoporosis." (PMID 38264287, 2023). "Furthermore, it also provided a theoretical basis for SIRT3 as a therapeutic target for osteoporosis." (PMID 35692409, 2022). "Interestingly, the silencing of SIRT3 can further strengthen the effect of AGEs, and the overexpression of SIRT3 can significantly reduce the occurrence of BMSCs aging and osteoporosis." (PMID 35692409, 2022). "The change in the expression of miR‐125b‐5p and the SIRT3/AMPK/mTOR axis, which was accompanied by the induction of autophagy, could be considered the underlying mechanism of the therapeutic properties of luteolin in confronting osteoporosis." (PMID 40104207, 2025). "Sirt3 may exert a dual role in osteoporosis through diverse pathways." (PMID 38264287, 2023). "In this review, SIRT3 could participate in several physiological processes including the senescence and differentiation of BMSCs, and osteoclastogenesis, thereby modulating osteoporosis." (PMID 35692409, 2022). "Importantly, cultured osteoclasts from mice exposed to radiation had significantly higher mRNA levels of mitochondrial deacetylase Sirt3—an essential protein for osteoclast mitochondrial activity and bone resorption in the development of osteoporosis —as compared to sham-irradiated mice." (PMID 34769141, 2021). "This article reviews the impact of various aspects of mitochondrial quality control on osteoporosis, focusing on how SIRT1, SIRT3, and SIRT6 can improve osteoporosis by regulating mitochondrial protein homeostasis, biogenesis, and mitophagy." (PMID 38264287, 2023). "While in terms of disuse osteoporosis, daphnetin up-regulated SOD2, eliminated ROS, restored SIRT3 expression and mitochondrial homeostasis in osteoclasts, resulting in inhibition of bone resorption." (PMID 36552574, 2022). "Sirtuin-3 (SIRT3), a NAD-dependent mitochondrial deacetylase, is essential for the enhanced mitochondrial function in osteoclasts and the increased bone resorption observed in osteoporosis." (PMID 40584154, 2025).
osteoporosis (continued). "Consequently, this article undertakes a comprehensive examination of the impacts of diverse facets of mitochondrial quality control on osteoporosis, as well as the influence of SIRT1, SIRT3, and SIRT6 on osteoporosis through the regulation of mitochondrial quality control." (PMID 38264287, 2023). "Targeting Sirt3 to improve mitophagy may protect against MSC senescence and senile osteoporosis." (PMID 36499074, 2022). "However, the specific effects and mechanisms of SIRT3 in osteoporosis are not clear." (PMID 35692409, 2022).
prostate carcinoma (24 papers, 2012 to 2025). A carcinoma that arises from epithelial cells of the prostate gland. "The next question was to determine the signaling pathway(s) that underlay the regulation of c-MYC stability by SIRT3 in prostate cancers." (PMID 26317998, 2015). "Taken together, these results implicated that SIRT3 was negatively correlated with clinical outcome of prostate cancer patients." (PMID 26317998, 2015). "We show a SIRT3-Akt-c-Myc signaling axis that underlies the progression of prostate cancer, and suggest that the molecular and pathological determination of SIRT3 may be used in prostate cancer diagnosis/prognosis." (PMID 26317998, 2015). "Collectively, our results unveiled SIRT3's tumor suppressive function and the underlying mechanism in prostate cancer, which might provide therapeutic implications for the disease." (PMID 26317998, 2015). "Conversely, in prostate cancer, SIRT3 suppresses the recruitment of macrophages and neutrophils to dampen the innate immune response and contribute to cancer progression." (PMID 38773972, 2024). "SIRT3 has also been shown to reduce the migration and epithelial‐to‐mesenchymal transition of prostate cancer cells." (PMID 38018900, 2024). "Put together, the authors concluded that SIRT3 inhibits the metastasis of prostate cancer via the Wnt/β-catenin/FOXO3A signaling axis." (PMID 36291902, 2022). "In this section, we discuss the mechanistic roles of nuclear (SIRT1, 6, and 7), cytoplasmic (SIRT2), and mitochondrial sirtuins (SIRT3, 4, and 5) in breast and prostate cancer." (PMID 36291902, 2022). "Consistent with this tumor suppressing effect of SIRT3, a recent study demonstrated that SIRT3 expression reduces the acetylation level of mitochondrial aconitase, leading to the reduction of prostate cancer growth." (PMID 36291902, 2022). "In this regard, further studies are needed to clarify the expression pattern of SIRT3 in prostate cancer tissues and cells." (PMID 36291902, 2022). "AR pathway activation also leads to SIRT3 transcriptional repression, thus enhancing mitochondrial aconitase activity and driving prostate cancer malignancy and bone invasion." (PMID 35328633, 2022). "Some studies have found that SIRT3 regulated prostate cancer procession by suppressing the necroptosis-involved innate immune response." (PMID 34769322, 2021). "For example, SIRT3 expression was significantly down-regulated in prostate cancer (PC), and it restrained the EMT and migration of PC cells through inactivating the promoted FOXO3A-mediated Wnt/β-catenin pathway." (PMID 33819917, 2021). "RelB suppression decreases the expression of the sirtuin SIRT3 and MnSOD, which in turn increases oxidative and metabolic stresses in prostate cancer cells." (PMID 33923601, 2021). "Our data showed that the expressions of both SIRT3 and SIRT6 are dramatically increased, which is closely linked with the overall survival of prostate cancer patients." (PMID 33282964, 2020). "The xenograft mouse model further showed that the SIRT3 and SIRT3 blockade enhances macrophage and neutrophil recruitment and thereby suppresses prostate cancer progress." (PMID 33282964, 2020). "The tumor suppressor role of SIRT3 in breast, colon, osteosarcoma and prostate cancer cells have been also reported." (PMID 28423723, 2017). "On the other hand, structure-based design of SIRT3 regulatory molecules should also be actively pursued and investigated for the treatment of prostate cancers." (PMID 26317998, 2015). "Overexpression of SIRT3 markedly reduced colony formation and cell viability of prostate cancer cells in vitro." (PMID 26317998, 2015). "Together these results demonstrated that overexpression of SIRT3 suppressed prostate cancer cell growth in vitro and in vivo." (PMID 26317998, 2015). "The gene copy number of SIRT3 in prostate cancer samples differentiated patients' prognosis, with the high copy number group showing significantly longer overall survival than the other group." (PMID 26317998, 2015).
prostate carcinoma (continued). "In SIRT3 overexpressed prostate cancer cells we transfected a constitutively active, myristoylated form of Akt (Myr-Akt), or applied LY294002, a selective inhibitor of the PI3K/Akt pathway to inhibit p-Akt Ser473 signals." (PMID 26317998, 2015). "We analyzed the phosphorylation of c-MYC at T58 and observed marked increase in two prostate cancer cell lines after SIRT3 overexpression." (PMID 26317998, 2015). "We have also shown that SIRT3 suppresses prostate cancer growth both in vitro and in vivo by inhibiting the activation of PI3K/Akt, thereby leading to the destruction of oncoprotein c-MYC." (PMID 26317998, 2015). "In this study, we have demonstrated for the first time that SIRT3 is moderately down-regulated in prostate cancers and patients with high SIRT3 copy number exhibit a significantly longer overall survival compared to those with low SIRT3 copy number." (PMID 26317998, 2015). "Together these data demonstrated that SIRT3 induced oncoprotein c-MYC destruction by stimulating ubiquitin-mediated proteolysis in prostate cancer cells." (PMID 26317998, 2015). "The p-Akt (Ser473) level was evidently reduced in the presence of NAC in SIRT3 silenced prostate cancer cells." (PMID 26317998, 2015). "Overexpression of SIRT3 by lentiviral transfection inhibited prostate cancer growth both in vitro and in vivo, whereas knockdown of SIRT3 increased prostate tumor growth." (PMID 26317998, 2015). "First, we examined datasets from Oncomine and found that in prostate cancer patients relatively higher SIRT3 mRNA expression level was correlated with lower c-MYC expression." (PMID 26317998, 2015). "Subcutaneous tumor formation assay by which tumor volume and dissected tumor weight was determined, clearly showed that knockdown of SIRT3 promoted prostate cancer growth in vivo." (PMID 26317998, 2015). "Mechanistically, the ubiquitination level of c-MYC was reduced and degradation of c-MYC was attenuated by the activation of Akt in SIRT3 overexpressed prostate cancer cells." (PMID 26317998, 2015). "To understand the molecular mechanism of SIRT3 in prostate cancer, we focused on specific oncoproteins." (PMID 26317998, 2015). "It is crucial to point out that SIRT3 suppresses prostate cancer progression through the inhibition of PI3K/Akt pathway and eventually down-regulation and destruction of oncoprotein c-MYC." (PMID 26317998, 2015). "To provide additional evidence in support of this notion, we performed immunohistochemical (IHC) staining of SIRT3 in primary tumors of prostate cancer patients (n=109, of which 32 biopsies were benign tissues, and 77 biopsies were tumor tissues)." (PMID 26317998, 2015). "The half-life of c-MYC protein was significantly reduced in SIRT3 overexpressed prostate cancer cells, in comparison with the vector group." (PMID 26317998, 2015). "Silencing of SIRT3 significantly promoted prostate cancer cell growth as determined by colony formation assay and cell viability assay." (PMID 26317998, 2015). "In vivo subdermal tumor formation assay confirmed the inhibitory effect of SIRT3 in prostate cancer." (PMID 26317998, 2015). "Analysis of a dataset containing 19 human clinical specimens showed that SIRT3 mRNA level in prostate carcinoma (PCa) was much lower than that in normal prostate tissues." (PMID 26317998, 2015). "SIRT3 functions as a cancer promoting factor in various types of cancer including pancreatic cancer, cholangiocarcinoma, liver cancer, gallbladder cancer, and prostate cancer." (PMID 38773972, 2024). "Importantly, SIRT3 expression has previously been shown to be downregulated in prostate cancer and knock‐in of SIRT3 in prostate cancer cells has been shown to have anti‐tumour effects." (PMID 38018900, 2024). "Similarly, mechanistic studies have been conducted in prostate cancer, which indicated that SIRT3 has a dual role in prostate carcinogenesis." (PMID 36291902, 2022).
prostate carcinoma (continued). "Furthermore, a recent study revealed that SIRT3 suppresses necroptosis-induced innate immunity to promote the progression of prostate cancer." (PMID 36291902, 2022). "The expression of SIRT3 in prostate cancer remains controversial." (PMID 36291902, 2022). "The authors concluded that SIRT3 has a pro-proliferative role in prostate cancers." (PMID 36291902, 2022). "Interestingly, an existing study documented the ability of sirtuin 3 (SIRT3) to regulate FOXO3a in prostate cancer." (PMID 33655712, 2021). "SIRT1 and SIRT3 may be up- or downregulated depending on the cancer type, acting either as oncogenes (e.g., colorectal or oral cancer), or tumor suppressors (e.g., SIRT1 in bladder cancer, SIRT1 and SIRT3 in breast and prostate cancer)." (PMID 32344886, 2020). "In this regard, developing small molecules to activate SIRT3 might be a sound strategy for prostate cancer treatment." (PMID 26317998, 2015). "Conversely, p-Akt Ser473 was enhanced by SIRT3 silencing in prostate cancer cells." (PMID 26317998, 2015). "In addition, forced expression of constitutively active Akt attenuated the inhibitory effect of SIRT3 showing up-regulation of p-Akt Ser473 levels and increased colony formation, whereas inhibition of Akt signaling suppressed prostate cancer cell growth." (PMID 26317998, 2015). "We hypothesized that SIRT3 might function by regulating the Akt pathway through ROS in prostate cancer." (PMID 26317998, 2015). "As SIRT3 effectively suppressed prostate cancer cell proliferation, we speculated that SIRT3 might function through the suppression of oncoprotein c-MYC." (PMID 26317998, 2015). "We found that SIRT3 was moderately down-regulated in prostate carcinomas." (PMID 26317998, 2015). "However, little is known about SIRT3's function in prostate cancer." (PMID 26317998, 2015). "We then tested whether SIRT3 knockdown could affect prostate cancer cell growth." (PMID 26317998, 2015). "Moreover, prostate cancer cells with higher SIRT3 protein level expressed lower c-MYC level." (PMID 26317998, 2015). "Up-regulation of SIRT3 might serve as new therapeutic strategies for prostate cancer." (PMID 26317998, 2015). "It is reported that SIRT3 inhibited RIPK3‐mediated necroptosis and innate immunity, promoting prostate cancer progression." (PMID 39501597, 2024). "The phosphorylation of RIPK3 can be suppressed by increased expression of SIRT3 and SIRT6 in prostate cancer, which induces the dysregulation of necroptosis." (PMID 35571098, 2022). "Transcriptional repression of SIRT3 enhances the ACO2 activity to promote mitochondrial citrate synthesis and adipogenesis, further promoting the progression of aggressive prostate cancer to the bone." (PMID 35832551, 2022). "Supporting a tumor suppressive function, SIRT3 expression in C42B and PC3 prostate cancer cells downregulated the expression of c-Myc, a well-established oncogenic protein." (PMID 36291902, 2022). "In prostate cancer, SIRT-3 and SIRT-6 can protect prostate cancer cells from necroptosis and reduce the overall survival." (PMID 34869390, 2021). "In summary, these results suggest that SIRT3 and SIRT6 promote prostate cancer progress by suppressing necroptosis-mediated immune response." (PMID 33282964, 2020). "Overall, our study identified that SIRT3 and SIRT6 are key regulators of necroptosis during prostate cancer progression." (PMID 33282964, 2020). "Mechanistically, we found that SIRT3 and SIRT6 promote prostate cancer progress by inhibiting RIPK3-mediated necroptosis and innate immune response." (PMID 33282964, 2020). "It has been reported that SIRT3 can increase the ubiquitination and degradation of the oncoprotein MYC and inhibit prostate cancer progression both in vitro and in vivo." (PMID 31817470, 2019).
prostate carcinoma (continued). "Previous studies have shown the ability of SIRT3 to activate FOXO3A and then to suppress EMT and the migration and invasion of prostate cancer cells." (PMID 31817470, 2019). "To confirm the regulation of SIRT3 on ROS levels and ACO2 activity in prostate cancer cells, we transfected DU145 and PC3 cells with siSIRT3 and evaluated ROS and citrate levels and ACO2 activity." (PMID 30972978, 2019). "In order to explore the function of SIRT3 in prostate cancer, we first generated two SIRT3 stably overexpressed, castration-resistant prostate cancer (CRPC) cell lines that originally expressed low levels of SIRT3 (C42B-SIRT3 and PC3-SIRT3)." (PMID 26317998, 2015). "Moreover, SIRT3 inhibits epithelial-mesenchymal transition (EMT) and migration by regulating FOXO3A expression and suppressing the Wnt/β-catenin pathway in prostate cancer." (PMID 35571098, 2022). "In a prostate cancer cell model, tumor-CAF contact triggers a sirtuin 3 -mediated regulation of HIF1 stabilization and glycolytic phenotype to upregulate MCT4 and enhance lactate secretion from CAFs, while prostate cancer cells increase lactate uptake mediated by MCT1." (PMID 32766253, 2020). "However, it is still unclear how SIRT3 and SIRT6 regulate RIPK1/RIPK3-mediated necroptosis and in turn maintain prostate cancer progress." (PMID 33282964, 2020). "To determine whether SIRT3 and SIRT6 are required for the growth of prostate cancer in vivo, we generated the LNCaP cell line with shRNA of SIRT3 and SIRT6 after doxycycline induction using a lentivirus transduction system." (PMID 33282964, 2020). "SIRT3 is involved in aging-related diseases including cancer, but its role in prostate cancer and detailed regulatory function are not known." (PMID 26317998, 2015). "We examined SIRT3's role on the degradation and ubiquitination of c-MYC in prostate cancer." (PMID 26317998, 2015). "Furthermore, the suppression of SIRT3 expression has been shown to enhance mitochondrial aconitase 2 (ACO2) activity, thereby facilitating mitochondrial citrate synthesis and contributing to the progression of prostate cancer." (PMID 38773972, 2024). "SIRT3 regulates the EMT-related markers such as E-Cadherin, N-Cadherin, and Vimentin to suppress EMT, especially in prostate cancer and small‐cell lung cancer, which may be related to Wnt/β-catenin/FOXO3α pathway and protein kinase B (AKT, also known as PKB)-dependent ferroptosis." (PMID 35832551, 2022).